TREM2 (triggering receptor expressed on myeloid cells 2)
Diseases named in the same sentence as TREM2 in open-access papers (continued):
Sharing a sentence is not in itself a finding about the gene and the disease.
Sepsis (continued). "To validate these observations in vivo, we established a cecal ligation and puncture (CLP) polymicrobial sepsis mouse model and assessed the expression pattern of TREM2." (PMID 39405126, 2024). "We then established a CLP sepsis mouse model with CPTIfl/fl and CPTIfl/fl Lyz2Cre mice following the treatment of TREM2 blocking Ab or control IgG Ab." (PMID 39405126, 2024). "TREM2 expression was markedly upregulated in sepsis patients and correlated with the severity of sepsis." (PMID 39405126, 2024). "Since effective bacterial clearance is crucial to preventing sepsis, we then explored the role of TREM2 in bacterial clearance." (PMID 39405126, 2024). "Meanwhile, the involvement of the SHP1/BTK axis in TREM2-mediated FAO regulation during sepsis was revealed." (PMID 39405126, 2024). "We found that TREM2 expression in monocytes was positively correlated with triglyceride concentration in sepsis patients." (PMID 39405126, 2024). "Consistent with the positive correlation between monocyte TREM2 expression and serum triglyceride concentration in sepsis patients, both systematic and macrophage-conditional knockout of TREM2 resulted in decreased serum triglyceride levels in sepsis mice." (PMID 39405126, 2024). "We demonstrated in this study that TREM2 accelerated sepsis by aggravating inflammatory responses, promoting organ damage, and inhibiting bacterial clearance." (PMID 39405126, 2024). "Research conducted in 2013 demonstrated that TREM2 protects against sepsis by enhancing bacterial clearance." (PMID 39113887, 2024). "To investigate the role of TREM2 in sepsis in vivo, we employed WT and TREM2-knockout (TREM2–/–) mice to establish sepsis mouse models and compared the symptoms induced by sepsis." (PMID 39405126, 2024). "Unsurprisingly, the levels of IL-1β, TNF-α, and IL-6 produced by TREM2+ monocytes were positively correlated with serum triglyceride concentrations of sepsis patients." (PMID 39405126, 2024). "Overall, we observed an increased expression of TREM2 in monocytes/macrophages in both sepsis patients and mice, suggesting a correlation of TREM2 with sepsis progression." (PMID 39405126, 2024). "We sorted TREM2+ versus TREM2– macrophages from sepsis mice and found that TREM2+ macrophages displayed an impaired bacterial killing activity compared with TREM2– macrophages after PA infection." (PMID 39405126, 2024). "Mechanically, we demonstrated that TREM2 interacted with the phosphatase SHP1 to inhibit bruton tyrosine kinase–mediated (BTK-mediated) FAO in sepsis." (PMID 39405126, 2024). "In sepsis, Trem2 has been identified as an inhibitor of pyroptosis in bone marrow-derived macrophages, suggesting its involvement involved in this process." (PMID 38348100, 2024). "Collectively, these results suggest TREM2+ macrophages as a subset of induced LAMs with proinflammatory properties under the condition of sepsis." (PMID 39405126, 2024). "Further investigation revealed that TREM2 promoted sepsis-induced inflammation and organ injuries by inhibiting FAO." (PMID 39405126, 2024). "To investigate the characteristics of TREM2-expressing macrophages in sepsis, we analyzed the transcriptional profiles of TREM2+ and TREM2– macrophages from previously reported single-cell RNA-Seq data on sepsis." (PMID 39405126, 2024). "Subsequently, we generated CPTIfl/fl TREM2fl/fl Lyz2Cre double-knockout mice, in which both CPTI and TREM2 are specifically deficient in macrophages, to further investigate the effects of TREM2 and CPTI on sepsis." (PMID 39405126, 2024). "As expected, TREM2 expression decreased in parallel with the gradual decline of CRP levels, suggesting a strong association of TREM2 with the severity of sepsis patients." (PMID 39405126, 2024). "In sepsis-induced cardiomyopathy, TREM2 is highly expressed in macrophage subcluster MAC1 cells, which play a role in maintaining mitochondrial homeostasis in cardiac myocytes." (PMID 39113887, 2024).
Sepsis (continued). "Our findings expand the understanding of sepsis pathogenesis and propose TREM2 as a potential therapeutic target for sepsis treatment." (PMID 39405126, 2024). "In this study, we identified TREM2 as a critical factor contributing to FAO impairment during sepsis." (PMID 39405126, 2024). "Since hyperglycemia and impaired FAO are implicated in the pathogenesis of sepsis and contribute to the mortality of sepsis patients, we next investigated the correlations of TREM2 with serum glucose and triglyceride levels." (PMID 39405126, 2024). "Knockout of TREM2 in macrophages improved the survival rate and reduced inflammation and organ injuries of sepsis mice." (PMID 39405126, 2024). "We further examined the expressions of rate-limiting enzyme CPTI and related molecules PPARα and PPARγ as well as its cofactors PGC-1α and PGC-1β to determine FAO levels in WT and TREM2–/– sepsis mice." (PMID 39405126, 2024). "As expected, the levels of sepsis-associated indicators including ALT, CRP, BUN, and creatinine (CREA2) were lower in TREM2–/– mice." (PMID 39405126, 2024). "Our findings suggest FAO recovery as a key mechanism by which TREM2 regulates inflammation, bacterial clearance, and organ injury in sepsis." (PMID 39405126, 2024). "A recent study found that TREM2 finely modulates the IL-23/IL-17A immune pathway to prolong survival and improve organ injury from sepsis in aged mice." (PMID 37435171, 2023). "In summary, we systematically investigated the inflammatory role of TREM2 in the central nervous system after sepsis using high concentrations of consecutive LPS injections to establish a mouse sepsis model." (PMID 36672106, 2023). "By combining single-cell RNA sequencing with fate mapping in a mouse model of sepsis, we demonstrate that the Mac1 subpopulation has distinct transcriptomic signatures enriched in endocytosis and displays high expression of TREM2 (TREM2hi)." (PMID 36635449, 2023). "Studies showed Trem-2 contributed to enhanced bacterial clearance in vivo and protected mouse from sepsis." (PMID 33794800, 2021). "Blocking TREM-2 in vivo by a recombinant protein in a polymicrobial sepsis model revealed that TREM-2 is required for bacterial clearance and improves survival." (PMID 27253382, 2016). "The administration of TREM2hi macrophages or the induction of TREM2 expression in macrophages may be a potential therapeutic approach for preventing and rescuing cardiac dysfunction in sepsis patients." (PMID 40083551, 2025). "Thus, delving into the mechanisms of TREM2 across diverse immune cells is paramount for unraveling the complexities of sepsis-induced lung injury and for identifying novel therapeutic targets in clinical practice." (PMID 40552184, 2025). "While this may appear as a daunting challenge, we can still draw upon the therapeutic effects and mechanisms of TREM2-targeted agents in other conditions to forge effective treatments for the intricate responses elicited by sepsis." (PMID 40552184, 2025). "We reveal that in severe CLP and bacterial sepsis models or LPS-induced acute endotoxemia, TREM2 displays a detrimental role and promotes inflammation, while in mid-grade sepsis, TREM2 may play different roles, which needs further investigation." (PMID 39959967, 2025). "The differences in the effect of TREM2 knockout on mortality between two severe CLP models are reasonable, because the varieties of pathogenesis and involved immune cells in different-severity sepsis may lead to the complexity of TREM2 function." (PMID 39959967, 2025). "The signaling pathways engaged by TREM2, particularly those entwined with NF-κB, are of paramount importance in the orchestration of inflammatory responses, playing a critical role in both the initiation and resolution of sepsis." (PMID 40552184, 2025). "Moreover, TREM2 fortifies the immune response against sepsis by engaging its ligand and activating signaling pathways that bolster macrophage survival and functionality." (PMID 40552184, 2025).
Sepsis (continued). "In summary, while TREM2 assumes a protective role in the modulation of immune responses during sepsis, its dysregulation may also culminate in adverse outcomes." (PMID 40552184, 2025). "Moreover, TREM2 influences the metabolic interplay between macrophages and hepatocytes, a critical factor in sustaining homeostasis during the tumultuous state of sepsis." (PMID 40552184, 2025). "Although some observations are contradictory, there are differences regarding TREM2 in intervening ways, sepsis models, mouse species, and administration routes, which may explain the discrepancies from these studies." (PMID 39405126, 2024). "Furthermore, the specific deficiency of TREM2 in macrophages decreased the production of IL-6, IL-1β, and TNF-α in the lung of sepsis mice." (PMID 39405126, 2024). "Furthermore, the transfer of TREM2+ monocytes accelerated the mortality of sepsis mice compared with TREM2– monocytes, further confirming the proinflammatory role of TREM2 in sepsis." (PMID 39405126, 2024). "To assess the impact of TREM2 on the recruitment of inflammatory cells, we analyzed the percentage of infiltrated inflammatory cells and observed reduced neutrophil and macrophage infiltration in the lung of TREM2–/– sepsis mice." (PMID 39405126, 2024). "Sepsis is characterized by excessive inflammation, cytokine storm, and organ damage, so we next assessed the levels of inflammation and organ injuries in WT and TREM2–/– mice." (PMID 39405126, 2024). "Our findings expand the understanding of FAO dysfunction in sepsis and reveal TREM2 as a critical regulator of FAO that may provide a promising target for the clinical treatment of sepsis." (PMID 39405126, 2024). "To further determine whether TREM2 directly influenced the outcome of sepsis, we transferred sorted TREM2+ and TREM2– monocytes from CD45.1 mice into CD45.2 recipient mice, followed by CLP challenge." (PMID 39405126, 2024). "Moreover, ibrutinib treatment also abolished the upregulated expression of CPTI induced by TREM2-Fc in monocytes from sepsis patients." (PMID 39405126, 2024). "Our observations may help explain the limited efficacy of single antiinflammatory therapies in sepsis and provide a promising strategy by targeting TREM2 to restore FAO and treat sepsis." (PMID 39405126, 2024). "Finally, we tested serum levels of clinical indexes for human sepsis evaluation in mice to comprehensively determine the in vivo effects of TREM2 during sepsis." (PMID 39405126, 2024). "Several studies report the protective effects of TREM2 on survival rates, organ damage, and inflammatory responses in metabolic dysfunction–associated steatotic liver disease–induced (MASLD-induced) or CLP sepsis mouse models." (PMID 39405126, 2024). "Currently, the in vivo role of TREM2 in sepsis is somewhat controversial." (PMID 39405126, 2024). "TREM2 knockout in macrophage alleviates sepsis-induced inflammation and organ damage." (PMID 39405126, 2024). "Trem2 ablation in macrophages impaired the ability of Mac1 cell self-renewal, which resulted in the accumulation of dysfunctional mitochondria in the extracellular space of myocardium and exacerbated cardiac function following sepsis." (PMID 36635449, 2023). "The authors focused on interpreting the alterations of tissue macrophages in a time-dependent fashion following the initial insult of cecal ligation and puncture, with an initial depletion of TREM2 positive macrophages and rapid restoration of TREM2 macrophages 7–21 days post the initial sepsis." (PMID 37453943, 2023). "Subsequently, we found that TREM-2 impairs the host defense against murine B. pseudomallei-induced sepsis, as demonstrated by an improved survival of infected Trem-2-/- mice as a direct result of diminished bacterial dissemination, decreased inflammation and less organ damage." (PMID 27253382, 2016).
Sepsis (continued). "The TREM superfamily also includes a sepsis-associated TREM1 and a soluble form of TREM2 which may extend TREM2 activities well beyond the cells in which they were initially generated." (PMID 26949937, 2016). "Thus, the intricate interplay of TREM2 in sepsis may herald a promising avenue for targeted therapeutic interventions aimed at the immune response in future endeavors." (PMID 40552184, 2025). "Thus, therapeutic strategies aimed at TREM2 may pave new pathways for the management of patients grappling with sepsis." (PMID 40552184, 2025). "Furthermore, the absence of TREM2 precipitates a dysregulation of macrophage function, exacerbating lung injury associated with sepsis, thereby indicating that the protective role of TREM2 in SI-ALI warrants considerable attention." (PMID 40552184, 2025). "Therefore, multiple studies have emphasized that targeting TREM2 might be a promising therapeutic strategy during sepsis." (PMID 40379629, 2025). "For instance, the absence of TREM2 is linked to compromised bacterial clearance and an escalated vulnerability to infection, thereby underscoring its pivotal role in the protective effects against sepsis." (PMID 40552184, 2025). "Since the elevated expression of TREM2 was observed in monocytes/macrophages during sepsis, we next generated TREM2 conditional knockout mice (TREM2fl/flLyz2Cre), in which TREM2 was specifically deleted in macrophages, to explore whether TREM2 exerted functions in sepsis via macrophages." (PMID 39405126, 2024). "Finally, we discuss the prospect of TREM2 as an interesting therapeutic target for sepsis." (PMID 38236825, 2024). "In addition, contradictions also exist in the bacterial clearance ability of TREM2 in sepsis." (PMID 39405126, 2024). "Likewise, CD63 was also largely induced in TREM2+ monocytes of sepsis patients." (PMID 39405126, 2024). "To explore the connection of TREM2 with FAO in sepsis, we isolated monocytes from the peripheral blood of healthy controls and sepsis patients and treated monocytes with recombinant TREM2-Fc protein to block TREM2 signaling, followed by the detection of FAO-related regulators." (PMID 39405126, 2024). "In addition, we discuss the therapeutic prospect of TREM2 in infectious diseases such as sepsis." (PMID 38236825, 2024). "Therefore, targeting and blocking TREM2 could be proposed as a candidate therapeutic strategy to fine-tune FAO dysfunction in sepsis." (PMID 39405126, 2024). "In a murine model of sepsis intertwined with non-alcoholic fatty liver disease (NAFLD), TREM2 is instrumental in preserving the metabolic harmony between macrophages and hepatocytes, ultimately improving liver energy supply and outcomes in sepsis." (PMID 40552184, 2025). "Future directions should include validating this mechanism in human sepsis, developing specific ADAM8 inhibitors, and exploring its interactions with related pathways such as TREM2 signaling." (PMID 41169382, 2025). "Furthermore, the influence of pathology-driven changes in blood composition, particularly in conditions with strong systemic inflammation (e.g., sepsis), in which altered leukocyte dynamics and soluble TREM2 levels may impact tracer distribution, is a potential limitation." (PMID 40639905, 2025). "In the current study, we found that the blockade of TREM2 restored FAO defects and potentially alleviated excessive inflammation and organ damage by promoting FAO in sepsis." (PMID 39405126, 2024). "The knockout of TREM2 in macrophages greatly restored the survival rates and FAO defects in sepsis mice." (PMID 39405126, 2024). "To further clarify the influence of BTK on TREM2-mediated effects in vivo, we treated Lyz2Cre and TREM2fl/fl Lyz2Cre mice with ibrutinib and subsequently established a CLP sepsis model to investigate the potential role of BTK." (PMID 39405126, 2024).
Sepsis (continued). "Meanwhile, about 26% of TREM2– CD45.1+ monocytes converted to TREM2+ monocytes following sepsis induction, indicating that sepsis induced TREM2 expression in monocytes." (PMID 39405126, 2024). "To further elucidate the effect of TREM2 on macrophage FAO, we isolated peritoneal macrophages (pMφ) and splenic macrophages from sepsis mice to evaluate their FAO rates ex vivo." (PMID 39405126, 2024). "Preliminary findings on sepsis showed that TREM1 amplifies systemic inflammatory response syndrome; in contrast, TREM2 negatively regulates TLRs." (PMID 38236825, 2024). "TREM-1 and TREM-2 are the most studied members of the TREM-family, however their exact role in the pathogenesis of sepsis remains ill-defined." (PMID 27253382, 2016). "Notably, HLA-DRA, IL1B, and CD86 were prominently elevated in Microglia 2 from sepsis patients, while P2RY12 and TREM2 were reduced, further supporting a pro-inflammatory shift." (PMID 41030458, 2025). "Consistently, we further observed that TREM2 expression was upregulated, while FAO rate-limiting enzyme carnitine palmitoyl transferase I (CPTI) and the regulator PCC-1α were downregulated in the monocytes of sepsis patients." (PMID 39405126, 2024). "Collectively, we revealed the role of TREM2 in aggravating sepsis and demonstrated that TREM2 blockade could alleviate sepsis through restoring FAO defects, which may provide an attractive therapeutic target for clinical sepsis manipulation." (PMID 39405126, 2024). "Surprisingly, we found that TREM2 blockade markedly improved the survival rate of sepsis mice, and l-carnitine administration did not further increase the survival rate of TREM2 Ab–treated mice." (PMID 39405126, 2024). "Results showed a positive correlation between TREM2 expression and serum triglyceride levels, but not glucose levels, in sepsis patients, further suggesting a link between TREM2 and lipid metabolism." (PMID 39405126, 2024). "Our results indicate that consecutive LPS injections attenuate the inflammatory response to sepsis by releasing IFN-β, resulting in the upregulation of TREM2 expression, which mediates the polarization of microglia from the M1 to M2 phenotype, reducing neuroinflammation." (PMID 36672106, 2023). "In addition, others have reported upregulation of TREM2 in response to porcine respiratory and reproductive syndrome virus (PRRSV) infection and polymicrobial sepsis." (PMID 35924849, 2022). "A similar effect was observed in a mouse model of sepsis where injection of myeloid cells overexpressing TREM2 enhanced bacterial phagocytosis and survival, but not if the mice were pretreated with LPS." (PMID 28768545, 2017). "In the same study it was shown that administration of TREM-2 overexpressing bone marrow derived myeloid cells improved survival during polymicrobial sepsis, but not endotoxaemia." (PMID 27253382, 2016). "Furthermore, TREM2-Fc treatment increased the phosphorylation of BTK in sorted monocytes from sepsis patients but not healthy donors." (PMID 39405126, 2024). "Following treatment with TREM2-Fc protein, the expressions of CD36, CPTI, and CPTII in monocytes were increased in sepsis patients but not in healthy controls, indicating an enhancement of FAO after TREM2 blockade during sepsis." (PMID 39405126, 2024). "A recent study indicates that the absence of TREM2 changes the exosome miRNA profile that alters the macrophage–hepatocyte metabolic coordination in MAFL and sepsis." (PMID 39172787, 2024).